TNF (tumor necrosis factor)
Diseases named in the same sentence as TNF in open-access papers (continued):
Sharing a sentence is not in itself a finding about the gene and the disease.
dry eye (continued). "TNF-α and IFN-γ have been showed to induce corneal epithelial barrier dysfunction, which is a key feature of dry eye, through downregulation of the corneal epithelial cell adhesion molecules of tight junctions." (PMID 34437596, 2021). "The significantly affected dry eye-related markers were correlated with significant changes in IL-6, IL-8, IFN-γ, and TNF-α levels." (PMID 34957146, 2021). "Proinflammatory cytokines IL-1, IL-6, IL-8, and HLA-DR activators TNF-α and IFN-γ were shown to be strongly correlated with dry eye markers, leading to ocular surface damage and goblet cell reduction." (PMID 34957146, 2021). "Omega 3 essential fatty acids: these fatty acids block production of IL-1 and TNFα and improve Schirmer test values, TBUT, OSDI, and meibomian gland function in patients with dry eye." (PMID 33050472, 2020). "The altered conjunctival cytology and reduced goblet cell counts reflect this inflammation at the ocular surface since TNF-α and IFN-ɣ induce apoptosis of goblet cells in experimental animals and dry eye patients." (PMID 32820183, 2020). "Treatment with HC eye drops significantly reduced the tear concentrations of TNF-α, IL-8, and MMP-9 vs. vehicle in the ConA dry eye model." (PMID 31680988, 2019). "Several studies have shown direct association and increased expression levels of inflammatory cytokines IL-6, TNF-α, MCP-1, and MMP-9 in tears of dry eye patients." (PMID 30519584, 2018). "In the dry eye group, the initial concentrations of IL-1β, IL-6, IL-8, MCP-1, TNF-α and IFN-γ were 57.78 ± 5.25, 214.73 ± 18.17, 500.30 ± 38.69, 1518.42 ± 143.29, 385.11 ± 21.95, and 96.55 ± 8.19 pg/ml, respectively." (PMID 27695117, 2016). "α-MSH at different doses decreased the transcript levels of TNF-α and IL-1β, and increased the levels of IFN-γ in the corneas and conjunctivas of the dry eye rats, suggesting an improvement on the microenvironment on ocular surface by this peptide." (PMID 26685899, 2015). "α-MSH at both 10−3 and 10−4 mg/ml significantly reduced TNF-α and IL-1β expression, as compared to the saline- and 10−5 mg/ml α-MSH-treated dry eye corneas and conjunctivas." (PMID 26685899, 2015). "The results showed that α-MSH at different doses ameliorated tear secretion, tear film stability, and corneal integrity, and corrected overexpression of proinflammatory factors, TNF-α, IL-1β, and IFN-γ, in ocular surface of the dry eye rats." (PMID 26685899, 2015). "Our present study provides convincing evidence that conjunctival explants produced proinflammatory mediators such as IL-1β, TNF-α and MMP-9 in response to air exposure for about 1 week, resembling in vivo dry eye pathophysiology." (PMID 24498087, 2014). "As in the case of TNF-α, the pro-inflammatory role of IFN-γ has been verified in experimental murine dry eye." (PMID 26605353, 2014). "We have previously shown increased expression of the pro-inflammatory cytokines TNF-α and IL-1β in ocular surface epithelia of the BTX-B lacrimal gland-injected dry eye mouse model." (PMID 22815633, 2012). "In an SS group, the concentrations of tear cytokines such as IL-17, TNF-a, and IL-6 were found to be significantly higher than in a non-SS dry eye group and control subjects." (PMID 40095328, 2025). "In this work, we developed an integrated, portable electrochemiluminescence (ECL)-based device for rapid and quantitative detection of tumor necrosis factor alpha (TNF-α), a pivotal inflammatory marker in ocular surface disease, with particular relevance to dry eye syndrome (DES)." (PMID 41149298, 2025). "The activated kinases initiate a cascade of protein phosphorylation involving multiple kinases and activate nuclear transcription factors, such as NF-KB, e.g., that the expression levels of TNF-α, IL-1β, and IL-6 were downregulated in BAC-induced dry eye after treatment with KIOM-2015E." (PMID 36499298, 2022).
dry eye (continued). "Previous studies have shown that mRNA expression levels of interleukin (IL)-1β, IL-6, IL-8, tumor necrosis factor (TNF)-α, interferon (IFN)-γ, and matrix metallopeptidase (MMP)-9 were significantly increased in tears and conjunctiva of dry eye patients compared to normal controls." (PMID 33921231, 2021). "Indeed, the ocular surface status in dry eye is affected by the pro-inflammatory mediators such as IL-1, IL-6, TGF-β, TNF-α, and MMP-9; neurotrophic factors such as NGF; and antigen-presenting cells." (PMID 32698387, 2020). "Delayed tear clearance increases the toxic cell waste products, environmental antigens and inflammatory mediator concentrations such as interleukin (IL)-1, tumor necrosis factor-α (TNF-α) and MMP-9 in the tear film and contribute to the pathogenesis or aggravate the severity of dry eye." (PMID 28661456, 2017). "An agonistic antibody (DTA-1) specific for GITR (glucocorticoid tumor necrosis factor) was administered 1 day after the injection of the ConA and TRI MS to determine whether the prevention of dry eye symptoms are mediated by the expanded Treg population." (PMID 29235530, 2017). "In contrast, etanercept, a TNF-alpha blocking antibody, administered as subcutaneous injections twice weekly, did not improve dry eye significantly compared to placebo injections." (PMID 29200970, 2017). "Indeed, animals with dry eye receiving CCR2 antagonist presented a decrease in corneal alterations and in pro-inflammatory cytokines TNF-α and IL-1β on the ocular surface, confirming the importance of CCL2 in the pathology." (PMID 27486749, 2016). "Dry eye also induces the secretion of cytokines such as IL6, IL-1β, TNF-α, and IFN-γ." (PMID 27555966, 2016). "TNF-α and MMP-9, which participate in the mitogen-activated protein kinase (MAPK) signaling pathways in ocular surface epithelial cells, have previously been detected in the corneal epithelium and are upregulated in patients with dry eye." (PMID 26937680, 2016). "The quantitative RT-PCR (qPCR) results showed the significant up-regulation in TNF-α, IL-1β, and IFN-γ mRNA levels in the saline-treated dry eye rats, as compared to the saline controls (D+NaCl vs NaCl+NaCl, p < 0.001 for TNF-α, p < 0.05 for IL-1β, p < 0.01 for IFN-γ)." (PMID 26685899, 2015). "Induction of dry eye did not affect TNF-α expression, which is consistent with the results from our previous study." (PMID 23049824, 2012). "TNF-α expression was not changed by induction of dry eye, while it was reduced in dry eye rats treated with 0.1% Se-lactoferrin eye drops." (PMID 23049824, 2012). "In previous studies, significantly increased levels of IL-1α, IL-6, and TNF-α RNA transcripts were found in the conjunctival epithelium in SS and non-SS dry eye patients compared with controls." (PMID 21976951, 2011). "Furthermore, the mRNA expression of tumor necrosis factor-α (TNF-α), interleukin-6 (IL-6), and IL-1β in HCECs is inhibited by RGD-Alg@MSCs, which indicated a strong anti-inflammatory effect, crucial for mitigating dry eye symptoms." (PMID 40991713, 2025). "The non-SS dry eye group showed significant changes in IL-1b, IL-10, and TNF-a, but not IL-8." (PMID 39408709, 2024). "IL-1α, TNF-α and Il-10 were not modified by dry-eye condition in comparison with the basal level." (PMID 34959420, 2021). "Inflammatory cytokines, like type I and type II interferons and IL-6, IL-1, and TNF-α as well as immunomodulatory cytokines like IL-10 and transforming growth factor β (TGF-β), have been identified as important players in SLE and are present in the tear of dry eye patients." (PMID 25893112, 2015). "Indeed, our results in this study demonstrated that α-MSH at different doses rectified the overexpression of the proinflammatory genes, TNF-α, IL-1β, and IFN-γ in the scopolamine-induced dry eye corneas and conjunctivas, suggesting the potent anti-inflammatory effects of this peptide." (PMID 26685899, 2015).
dry eye (continued). "The evolution of the dry eye condition was assessed by histology, immunohistochemistry staining, scanning electron microscopy, and gene expression by using TaqMan gene assay technology (mucin-4 [MUC4], matrix metallopeptidase-9 [MMP9], tumor necrosis factor-α [TNF-α], and defensin β-2 [DEFB2)." (PMID 21245952, 2011). "We also show, for the first time, that rhPRG4 downregulates TNFα-induced FAT10 expression, and this protein has not been previously studied in the context of dry eye but does play a proinflammatory role in other diseases." (PMID 36361504, 2022). "Five inflammatory cytokines IL-1β, TNF-α, IL-6, IL-8, and IFN-γ, were examined and compared between subjects with and without dry eye." (PMID 34957146, 2021). "In the no dry eye group, 1 day postoperative concentration of IL-1β, IL-6, IL-8, MCP-1, TNF-α and IFN-γ were 51.42 ± 6.05, 119.51 ± 12.19, 443.92 ± 34.51, 2128.74 ± 215.64, 159.73 ± 12.98, and 51.54 ± 6.82 pg/ml, respectively." (PMID 27695117, 2016). "In the no dry eye group, the initial concentrations of IL-1β, IL-6, IL-8, MCP-1, TNF-α and IFN-γ were 2.11 ± 0.14, 13.36 ± 1.97, 143.83 ± 11.92, 55.49 ± 5.94, 9.04 ± 0.01 and 0.55 ± 0.19pg/ml, respectively." (PMID 27695117, 2016). "In this study, fluorometholone showed significant inhibition of IL-1β and TNF-α expression of ocular surface epithelia and improvement of corneal fluorescein staining in the BTX-B dry eye mouse model, but did not change the tear production." (PMID 22815633, 2012).
Infertility (119 papers, 2008 to 2026). "Concurrently, pro-inflammatory mediators like interleukin-6 (IL-6), interleukin-8 (IL-8), and tumor necrosis factor-alpha (TNF-α) are frequently found in the seminal plasma of infertile men and are linked to poor semen parameters and testicular dysfunction." (PMID 41750676, 2026). "Abnormally elevated TNF-α levels can cause pelvic adhesions, leading to diseases such as miscarriages and infertility." (PMID 40837367, 2025). "The diagnostic sensitivity and specificity of GLUT4, LEPR, and TNF-α combined assay for PCOSinduced infertility in PCOS women were 88.57% and 75.00%, respectively, and those for PCOS in healthy women were 78.57% and 60.00%, respectively (P<0.05)." (PMID 39991169, 2025). "The current consensus is that dysregulated pelvic inflammation plays a crucial role in EMS, as evidenced by the fact that increased TNF-α levels are closely associated with the pelvic pain and infertility caused by EMS." (PMID 35784569, 2022). "Leukocytospermia is an established marker of inflammation and it has been associated with increased semen levels of interleukin-6 and tumor necrosis factor-α, both inflammatory cytokines, in infertile patients." (PMID 33226627, 2021). "It is unclear what specifically induces these alterations in the oocytes, but inducers such as TNF- α, and ROS associated with oxidative stress have been shown to alter the oocyte morphology and spindle dynamics contributing to infertility." (PMID 22536401, 2012). "We postulate that the early loss of testosterone, TAF7, and TNF may cause infertility in males following Busulfan genotoxicity in the testis." (PMID 39457533, 2024). "And increased production of TNF caused by the activated macrophages and biological effect of IL-17 on endometrial cells accelerates the occurrence of endometriotic lesions accompanied by infertility and unexplained pelvic pain." (PMID 35582411, 2022). "An exaggerated Th1 response is thought to be detrimental to the process of embryo implantation and has been linked to infertility; therefore, elevated tumour necrosis factor (TNF) levels have been targeted for therapeutic correction in patients with a raised Th1/Th2 ratio." (PMID 32378442, 2020). "Previous studies have linked TNFα to infertility in C. trachomatis-infected women." (PMID 32127796, 2020). "When the studied TGFB3/TNF genotypes were analyzed for the presence of potential association with sperm parameters, no significant genotype-dependent differences were observed among infertile men." (PMID 26612435, 2015). "In human, both IFN-γ and TNF-α have been reported to be associated with infertility." (PMID 18489796, 2008). "In this study, given that TNFα is an importantregulator of steroidogenesis and may affect spermatogenesis,we investigated the association of theTNFα -308 G/A SNP with different kinds of spermabnormality in infertile males of Iranian origin." (PMID 28670429, 2017). "From the present study it can be suggested that the enhanced HSP expression leads to antigen specific increase in IFN-γ, IL-10 and TNF-α at the site of infection by cervical mononuclear cells suggesting cHSPs may consequently contribute to the immunopathogenesis associated with the infertility." (PMID 18489796, 2008). "GLUT4, LEPR, and TNF-α levels in the peripheral blood were detected in all participants, and their diagnostic value for PCOS in healthy women and PCOS-induced infertility in PCOS patients was analyzed." (PMID 39991169, 2025). "The IMMUNOX panel was recently proposed as a new diagnostic criterion for unexplained infertility and is composed of four biomarkers: Glycodelin (GLY), Tumor Necrosis Factor-α (TNFα), Complement Activation Toxic Factor (CATF), and Total Oxidative Status (TOS)." (PMID 38399492, 2024). "Clinical value of tumor necrosis factor (TNF) inhibitors in in vitro fertilization-embryo transfer (IVF-ET) in infertile women with polycystic ovary syndrome (PCOS) was investigated in this study." (PMID 37055769, 2023).
Infertility (continued). "Pro-inflammatory cytokine IL-1β was significantly dysregulated while TNF-α and IL-6 were noticeably increased in infertile males, considering the possibility of cholinergic-mediated systemic inflammation in male infertility." (PMID 37027384, 2023). "In other words, TNF-α inhibitors have a certain application value for IVF-ET in infertile women with PCOS." (PMID 37055769, 2023). "Collectively, after application of TNF-α inhibitor regimen, superior overall treatment effect can be observed in infertile PCOS patients receiving IVF-ET." (PMID 37055769, 2023). "Inflammation is a crucial factor in male infertility, and higher seminal plasma concentrations of IL-1, IL-6, interferon-γ, and TNF-α have been found in infertile patients compared to normal controls." (PMID 38077946, 2023). "The presence of activated macrophages, cytokines, elevated TNF-alpha levels, heightened growth factors, and oxidative stress (OS) within the peritoneal fluid (PF) of infertile women affected by EMS can potentially exert toxic effects on sperm function." (PMID 38002087, 2023). "First, women with severe infertility were positioned on their list since the mean ratio of Th1/Th2 (TNFα/IL-4) was greater than the ratio of Th1/Th2 in infertile women and women with IVF failure." (PMID 36937474, 2023). "This suggests that TNF-α inhibitors contribute to conception in infertile patients with PCOS undergoing IVF-ET." (PMID 37055769, 2023). "In particular, the effect of Pb exposure on cytokines such as tumor necrosis factor-alpha (TNF-α) and interleukin-8 (IL-8) is linked to infertility and cardiomyopathies in adults." (PMID 37107878, 2023). "Previous studies have shown that the concentrations of TNFα and IL-6 were higher in the blood and follicular fluid of infertile women with PCOS than in the control group." (PMID 35928256, 2022). "Further studies on protein levels are needed to clarify the role of TNF-⍺ and IFN-γ as a prognostic value in evaluating the recurrent abortion risk in infertile male partners." (PMID 35360193, 2022). "At the same time, increased TNF-α can directly reduce the capacity of endometrial tissue glucose uptake, affect endometrial function, and lead to infertility." (PMID 35600955, 2022). "Upregulated TNF-α increases atresia follicles in ovaries, implicating in the development of infertility." (PMID 34135985, 2021). "The molecules most involved in infertility are interleukin (IL) -1, IL-2, IL-6, IL-8, interferon-ɣ, and tumor necrosis factor-α (TNF-α)." (PMID 33925640, 2021). "In our study, we used the HEC-1A and HEC-1B cell lines treated with TNFα and IFNγ to model possible fertile/infertile pathologies." (PMID 33596915, 2021). "In summary, in fertile and infertile patients’s seminal plasma, the expression of cytokines (TNF-α, IL-6), miRNAs (miR-146a-5p, miR-34a-5p, miR-23a-3p) and IL-1α protein was not strongly correlated to any standard sperm parameters." (PMID 34319544, 2021). "Curcumin nanomicelle improved semen parameters and testosterone levels, reduced FSH, LH, and prolactin, and improved oxidative stress through the reduction of serum MDA, CRP, and TNF and by increasing the serum total antioxidant capacity in infertile males." (PMID 34829704, 2021). "As previously reported, the serum levels of TNF-α and IL-6 were higher in the secondary infertility group compared to the uterine fibroids group." (PMID 33092547, 2020). "Although the activation of TLR4, and the expression of IL-1β and TNF-α, provides an essential host immune defence mechanism, they are also involved in different aspects of infertility." (PMID 32064024, 2020). "A potential reproductive benefit of anti-TNF-α agents, adalimumab (Humira), etanercept (Enbrel), and infliximab (Remicaid) has been proposed in infertile women with abnormal immunological parameters." (PMID 32378442, 2020). "Cytokines, like TNF-α, selected ILs and others which trigger a Th1 type immune response, are suspected to play a major role in infertility." (PMID 30518097, 2018).